RFPL1 (ret finger protein like 1)
Description:
Negatively regulates the G2-M phase transition, possibly by promoting cyclin B1/CCNB1 and CDK1 proteasomal degradation and thereby preventing their accumulation during interphase.
Synonyms: RNF78
Tractability: Antibody: the Human Protein Atlas places it where antibodies can reach.
Gene: Protein-coding gene on chromosome 22 (29,438,583 to 29,442,455, forward strand). Ensembl gene ENSG00000128250.
Subcellular location: Cytoplasm; Nucleus
Subcellular location (Human Protein Atlas): Nuclear speckles; Plasma membrane
Gene Ontology:
Molecular function: ubiquitin protein ligase activity
Biological process: negative regulation of G2/M transition of mitotic cell cycle; positive regulation of proteasomal ubiquitin-dependent protein catabolic process; innate immune response; regulation of gene expression
Cellular component: cytoplasm; nucleus
Genetic constraint (gnomAD): Loss-of-function variants: 6 observed, 8.79 expected, observed/expected ratio (o/e) 0.68, 90% interval 0.37 to 1.34. That is too few expected variants to judge how well the gene tolerates losing a copy. Missense variants: 349 observed, 406.17 expected, observed/expected ratio (o/e) 0.86, 90% interval 0.79 to 0.94. Synonymous variants: 144 observed, 151.22 expected, observed/expected ratio (o/e) 0.95, 90% interval 0.83 to 1.09.
Homologues: Orthologues: macaque RFPL1 (90% identical). Paralogues in human: RFPL3 (92% identical), RFPL2 (85% identical), RFPL4A (52% identical), RFPL4AL1 (52% identical), RFPL4B (30% identical), RNF135 (17% identical), SPRYD4 (11% identical), RNF152 (7% identical), CD86 (6% identical), CD274 (6% identical), PDCD1LG2 (5% identical), CD80 (5% identical).